KLF15 (KLF transcription factor 15)
Diseases named in the same sentence as KLF15 in open-access papers (continued):
Sharing a sentence is not in itself a finding about the gene and the disease.
Obesity (23 papers, 2013 to 2025). Accumulation of substantial excess body fat. "Consistently, found an increase in UCP-1 through Kruppel-like factor 15 (KLF15), linked to brown adipocytes that represent a crucial phenotype for protection against obesity." (PMID 38915405, 2024). "We demonstrated for the first time that KLF15 acts as a novel regulator of adipolin expression in adipocytes and that the pro-inflammatory states caused by obesity lead to reduction of adipose adipolin expression via suppression of KLF15 activation." (PMID 24358263, 2013). "In vitro, animal, and human studies have demonstrated that allicin, via the KLF15 signaling cascade, can prevent obesity and related metabolic disorders by increasing the expression of genes specific to brown adipocytes, such as UCP-1." (PMID 40087612, 2025). "Inflammatory conditions, fibrosis, obesity, cardiovascular diseases, and cancer can be altered by factor KLF15." (PMID 37886924, 2023). "Metabolic characterization of Klf15 knockout (KO) mice, and more recently of muscle-specific Klf15 KO mice (K15-SKO), demonstrates pronounced defects in lipid utilization, decreased exercise capacity, and susceptibility to diet-induced obesity." (PMID 35413288, 2022). "In the present study, we provide evidence that KLF15 was decreased in visceral adipose tissue of obesity subjects and high-fat diet (HFD) mice." (PMID 34802421, 2021). "More importantly, KLF15 levels were significantly and negatively correlated with WC, WHR, Weight, BMI, and TG, suggesting KLF15 levels were correlated with obesity state." (PMID 34802421, 2021). "The results showed that KLF15 levels were significantly and negatively correlated with WC, WHR, weight, BMI, and TG, suggesting KLF15 levels were correlated with obesity state (P < 0.05)." (PMID 34802421, 2021). "Emerging evidence has demonstrated that allicin induces white adipocyte browning and reduces high-fat-induced obesity via the KLF15 signaling cascade." (PMID 31810206, 2019). "We identified a mouse strain, HLB444, carrying an N-ethyl-N-nitrosourea (ENU)-induced mutation in a highly conserved C2H2 zinc-finger DNA binding motif of the transcriptional regulator KLF15 that exhibits resistance to diet-induced obesity." (PMID 31553739, 2019). "In obesity, there is muscular atrophy due to increased cortisol levels due to changes in Kruppel-like factor 15 (KLF15) in skeletal muscle." (PMID 28413737, 2017). "Strategies to normalize or enhance adipolin production by targeting KLF15 can be valuable for the treatment or prevention of metabolic dysfunction in obesity." (PMID 24358263, 2013). "To evaluate the metabolic effects of diet-induced obesity in KLF15-/- mice, we placed 3-4 month-old male WT and KLF15-/- mice on a high-fat diet (HFD; 60% kcal from fat) for 14 weeks." (PMID 24167585, 2013). "Therefore, REGγ regulates browning of WAT by degrading KLF15 through ubiquitin‐ and ATP‐independent protein degradation pathways to induce obesity." (PMID 40971725, 2025). "In contrast to KLF15, furin, promotes obesity-induced inflammatory conditions by stimulating TNFα release from adipose tissue, modulating the activities of adipocytokines (including adipolin), thereby intensifying the vicious cycle caused by the inflammatory response and insulin resistance." (PMID 39308032, 2024). "The profound metabolic derangements observed in Klf15-deficient animals (i.e., obesity, dyslipidemia, nonalcoholic fatty liver disease, etc.)suggest that KLF15 critically interacts with other transcription factors in these metabolic networks." (PMID 35413288, 2022). "KLF15 was decreased in visceral adipose tissue of obesity subjects and high-fat diet (HFD) mice." (PMID 34802421, 2021). "Here, we showed that KLF15 is decreased in omental adipose tissue of obesity subjects." (PMID 34802421, 2021). "Thus, it is likely that adipose tissue inflammation in obesity contributes to reduction of adipolin expression partly through down-regulation of KLF15." (PMID 33275602, 2020).
Obesity (continued). "Above all, our findings suggest that, in obese status, the lower expression level of A2bAR, KLF4, and KLF15 of visceral adipose tissue may correlate with obesity-dyslipidemia induced inflammation in Uygur population." (PMID 27199507, 2016). "Thus, KLF15/PPARα may interact with Sirt3 to regulate Sirt3 activity or expression in response to obesity and thus regulate ACADVL acetylation." (PMID 30061171, 2018). "The mRNA expression profile chip analysis by our previous research has demonstrated that mRNA expression levels of KLF4 and KLF15 were significantly decreased in subjects with obesity, suggesting these genes may play an important role in lipid metabolism in Uygur population." (PMID 27199507, 2016). "Thus, our study intends to evaluate the mRNA expression level of A2bAR, KLF4/KLF15, and key inflammation signaling pathway genes in visceral adipose tissue from Uygur population to investigate the correlation of A2bAR and KLF4/KLF15 with obesity-dyslipidemia induced inflammation in Uygur population." (PMID 27199507, 2016). "However, we cannot exclude the possibility that obesity-induced perturbations in the balance between KLF15 and KLF3 expression may affect adipolin expression." (PMID 24358263, 2013). "Allicin has also been identified as a potential preventive agent for obesity and related metabolic diseases by increasing the expression of brown adipocyte-specific genes such as UCP-1 through the KLF15 signaling cascade." (PMID 40087612, 2025). "This suggests that the spinach-thylakoid extract and HIFT, alone or in combination increases KLF15 and CTRP12 levels in obese individuals, while decreases in furin mediate reversal of obesity-induced inflammatory conditions." (PMID 39308032, 2024). "Our study discovers a new key function for the TBX15 TF in trans regulating an adipose co-expression network of 347 adipose, mitochondrial, and metabolically important genes, including PPARG, KLF15, PPARA, ADIPOQ, and 35 obesity GWAS genes." (PMID 34340684, 2021). "Our study discovers a novel key function for the TBX15 TF in trans regulating an adipose co-expression network of 347 adipose, mitochondrial, and metabolically important genes, including PPARG, KLF15, PPARA, ADIPOQ, and 35 obesity GWAS genes." (PMID 34340684, 2021). "Obviously, this study demonstrated that KLF15 protein expression was substantially increased and the phosphorylation of p38 MAPK was significantly decreased after blocking GPR120 in obesity animal model." (PMID 34802421, 2021). "Increase in KLF15 mRNA levels was observed in class I obese patients but it remained unaltered in class II and III obesity." (PMID 32903728, 2020). "This article presents the first ever report on the impact of spinach thylakoid extract-induced high-intensity functional training (HIFT) on obesity management via regulating the levels of novel adipokine, C1q/TNF-related Protein-12 (CTRP-12), furin, and Krüppel-like factor 15 (KLF-15)." (PMID 39308032, 2024). "To test this hypothesis, we investigated the impact of spinach thylakoid extract and 12-week HIFT on obesity markers and the levels of novel adipokines such as CTRP-12, furin, and KLF15 that are involved in metabolic homeostasis." (PMID 39308032, 2024). "The proposed combination intervention may reverse obesity-induced insulin resistance and metabolic dysfunctions by positive regulation of CTRP-12/adipolin and KLF15 and simultaneous suppression of furin levels." (PMID 39308032, 2024). "To study the effect of the HFD-induced obesity in the GCs response, we assessed the dexamethasone-induced expression of FKBP51, PDK4, and KLF15 as readouts to evaluate GC response in the liver, skeletal muscle (gastrocnemius), and white adipose tissue (epididymal fat)." (PMID 33066464, 2020).
Obesity (continued). "Our observations demonstrate that adipose KLF15 but not KLF3 was down-regulated by obesity or the inflammatory stimulus, suggesting that KLF3 has a minor role in regulation of adipolin expression in fat tissue under conditions of obesity." (PMID 24358263, 2013). "KLF15, CEBPA, and CEBPB are crucial for the early stages of adipocyte differentiation, and their downregulation in ASCs may reflect a shift away from adipogenic potential as obesity progresses." (PMID 40518865, 2025). "Altered DNA methylation in promoters of transcription factor genes (PPARA, KLF15, NR3C1, RORA and ATF4) known to regulate FGF21 expression and its binding receptors and co-factors (FGFR1, FGFR3 and FGFRL1 and KLB) has been revealed in relation to the elevated levels of circulating FGF21 in obesity." (PMID 33670024, 2021).
Insulin resistance (17 papers, 2013 to 2025). Increased resistance towards insulin, that is, diminished effectiveness of insulin in reducing blood glucose levels. "A key finding in this study is that KLF15 deficiency results in the uncoupling of hepatic ER stress and insulin resistance." (PMID 24167585, 2013). "KLF15-deficient mice could slow down the absorption of lipids or other nutrients and fight against insulin resistance induced by a high-fat diet." (PMID 36755591, 2023). "In high-fat feeding, KLF15−/− mice were resistant to hepatic insulin resistance and fatty liver and responded to pharmacological induction of endoplasmic reticulum stress." (PMID 36937859, 2023). "KLF15 has also been studied for its contribution to hepatic lipid metabolism and insulin resistance." (PMID 36902112, 2023). "For other members of the SP/KLF family, such as KLF15, the role is more complex as there are reports that both support and oppose its contribution to hepatic insulin resistance and hypertriglyceridemia." (PMID 36902112, 2023). "Deletion of the KLF15 gene can improve insulin resistance in mice under the influence of high-fat diet (HFD) but does not affect endoplasmic reticulum stress and hepatic inflammatory response with insulin resistance." (PMID 36937859, 2023). "Mice with skeletal muscle deletion of KLF15 showed insulin resistance, glucose intolerance, and increased lipid deposition." (PMID 35682902, 2022). "KLF15 has previously been reported to be down-regulated in subcutaneous WAT and skeletal muscle from subjects with systemic insulin resistance, thus supporting an important role for KLF15 not only in adipose tissue but in systemic insulin resistance." (PMID 28570579, 2017). "We now show that KLF15 plays an essential role in ER stress-mediated insulin resistance in the liver." (PMID 24167585, 2013). "Further, a marked increase in uncoupling protein 3 (Ucp3) and Krüppel-like factor 15 (Klf15) expression in the skeletal muscle may promote lipid utilization and help mitigate lipid-induced insulin resistance in Ctrp10 KO female mice." (PMID 37961647, 2025). "In addition, after endoplasmic reticulum stress was activated, the liver stress response of KLF15−/− mice was significantly reduced when hepatic steatosis and insulin resistance were induced." (PMID 36937859, 2023). "This uncoupling of ER stress and insulin resistance in HFD-fed Klf15−/− mice is explained by the possible induction of 5′-AMP-activated protein kinase (AMPK) and inhibition of mTORC1 signaling and stimulation of PGC-1α, leading to increased fatty acid oxidation." (PMID 36902112, 2023). "In contrast to these earlier findings, where KLF15 has been identified for its pathological role in HFD-induced insulin resistance and hepatic steatosis, under fasting conditions, KLF15 was identified to inhibit hepatic lipogenesis by suppressing the Srebf1c transcription." (PMID 36902112, 2023). "In addition, a possible role for hepatic KLF15 in ER stress-related insulin resistance has been identified in animal models." (PMID 36902112, 2023). "In turn, the increased circulating BCAA levels experienced by obese individuals may lead to hyperactivation of the mTOR pathway that worsens systemic insulin resistance and KLF15 transcription, thus forming a vicious cycle." (PMID 35634382, 2022). "In particular KLF15 could play and important role in development of systemic insulin resistance, as it has also been shown to have effects in other tissues." (PMID 28570579, 2017). "Interestingly, in analysis of gene sets over-represented among these 66 KLF15-target genes compared to all analyzed genes expressed in the cells, insulin resistance scored highest (adjusted P 9.7x10-5)." (PMID 28570579, 2017). "Moreover, KLF15 knockout mice are protected against insulin resistance under high-fat feeding conditions." (PMID 25815008, 2015).
Insulin resistance (continued). "Our data indicate that uncoupling of ER stress and insulin resistance results from liver autonomous effects of KLF15 deficiency and is independent of dietary conditions." (PMID 24167585, 2013). "However, KLF15-/- mice are protected against ER stress-induced hepatic insulin resistance and steatosis compared to WT controls." (PMID 24167585, 2013). "Furthermore, in primary hepatocytes, KLF15 deficiency markedly inhibits activation of mTORC1 by amino acids and insulin, suggesting a mechanism by which KLF15 controls mTORC1-mediated insulin resistance." (PMID 24167585, 2013). "Thus, deletion of KLF15 gene may lead to insulin resistance or steatosis at obese patients with HFD and uncoupling of endoplasmic reticulum stress and inflammatory response." (PMID 36937859, 2023). "Therefore, gene intervention targeting the KLF15 gene can improve HFD-induced insulin resistance." (PMID 36937859, 2023). "Our data suggest that the ability of KLF15-/- mice to maintain a low energy state, particularly under high-fat feeding conditions, prevents the upregulation of mTORC1 activity and inhibition of autophagy that, in concert with ER stress signaling, lead to hepatic insulin resistance." (PMID 24167585, 2013). "Because KLF15-/- mice show indications of chronic ER stress but remain insulin sensitive compared to WT littermates, we hypothesized that KLF15 may mediate ER stress-induced insulin resistance." (PMID 24167585, 2013). "To further explore potential mechanisms underlying the protection against ER stress-induced insulin resistance in KLF15-/- liver, we determined whether the absence of KLF15 might inhibit activation of proinflammatory cytokines and/or JNK." (PMID 24167585, 2013). "In addition, the maintenance of increased autophagic flux may be a mechanism by which KLF15-/- mice are protected against high-fat diet-induced insulin resistance." (PMID 24167585, 2013). "During conditions of insulin resistance, the activity of WWP1 is reduced, which inhibits UPP-dependent KLF15 degradation, thereby increasing the levels of KLF15." (PMID 39433511, 2024). "Here we identify the transcription factor, Kruppel-like factor 15 (KLF15), as an essential mediator of ER stress-induced insulin resistance in the liver." (PMID 24167585, 2013). "Klf15 deletion ameliorates hepatic insulin resistance induced by a high-fat diet (HFD) without affecting the endoplasmic reticulum (ER) stress or hepatic inflammatory responses that typically accompany insulin resistance." (PMID 29942807, 2018). "By transcriptome profiling in a large human cohort including non-obese and obese with or without insulin resistance, combined with functional evaluation in adipocyte cultures of specific genes, this study identifies KLF15 and SLC25A10 as potential modulators of adipocyte insulin sensitivity." (PMID 28570579, 2017). "Additionally, insulin resistance has been demonstrated for both the transgenic and adipose-specific KO strains, while it was not seen in HLB444 or the Klf15-/- KO." (PMID 31553739, 2019). "We conclude that the absence of KLF15 causes increased hepatic JNK activity and inflammation independent of diet-induced metabolic effects and that KLF15 may be required for both JNK and inflammation-mediated insulin resistance in liver." (PMID 24167585, 2013).
heart failure (16 papers, 2012 to 2025). Inability of the heart to pump blood at an adequate rate to meet tissue metabolic requirements. "In a preliminary analysis, we explored the association between LVH, KLF15 genotype and heart failure outcomes in the discovery cohort." (PMID 28400202, 2017). "The presence of fibrosis is another characteristic of LVH and heart failure, and KLF15 has also been implicated in this process." (PMID 22586493, 2012). "At the same time, the inflammatory response and oxidative stress, which were previously under the rhythmic control of KLF15, were also abnormally aggravated, causing more serious myocardial damage and accelerating the process of cardiac failure after myocardial infarction." (PMID 40429972, 2025). "The KLF15 rs9838915 A allele predicted the first hospitalization with heart failure." (PMID 29702551, 2018). "The KLF15 genetic variant was also associated with first heart failure hospitalization." (PMID 28400202, 2017). "From birth, KLF15 accumulates in the heart and decreases in heart failure, a trend similar to the pattern of lipid oxidation." (PMID 40429972, 2025). "Downregulation of KLF15 has also been found in rodent models of heart failure and in failing human hearts." (PMID 31553739, 2019). "Conversely, suppression of KLF15 has been shown to occur in heart failure, an expression pattern that closely reflects lipid utilization." (PMID 30089854, 2019). "We also determined if the KLF15 SNPs predicted the adverse consequence of heart failure hospitalization." (PMID 28400202, 2017). "Systemic deletion of KLF15 results in reduced fatty acid oxidation in the isolated working heart model as well as enhanced heart failure following pressure overload." (PMID 25815008, 2015). "Mouse studies showed that somatic loss of KLF15 results in increased susceptibility to pressure overload-induced LVH and heart failure." (PMID 22586493, 2012). "The expression of KLF15 is consistently down-regulated during pathological hypertrophy and heart failure as was shown in animal models and patients with aortic stenosis and non-ischemic cardiomyopathy." (PMID 22586493, 2012). "Interplay concerning KLF15-Wnt dynamics defines the network control of cardiomyocyte and vascular cell homeostasis in the postnatal heart and demonstrates its potential as a cardiac-specific therapeutic target in heart failure." (PMID 39795113, 2024). "Our results have clinical relevance as there is evidence that loss of cardiac KLF15 may contribute to LVH and the progression to heart failure in humans." (PMID 29970016, 2018). "Genetic variants in KLF15 may also contribute to the development of LVH and predict heart failure outcomes in those with LVH." (PMID 29702551, 2018). "The authors propose that loss of KLF15 is not a response to heart failure but that loss of KLF15 contributes to progression to heart failure by removing the ability to repress key cardiac transcription factors that enable growth." (PMID 29702551, 2018). "In conclusion, the fact that cardiomyocyte-specific KLF15 overexpression may reduce cardiomyocyte hypertrophy seems beneficial and suggests that KLF15 may be used as a therapeutic target for hypertrophy and heart failure." (PMID 22586493, 2012). "In vivo in rats, KLF15 expression is down regulated in response to pressure overload induced by trans-aortic constriction (TAC), and in the Ren-2 model of hypertension induced LVH, loss of the constitutive presence of cardiac KLF15 precedes progression to heart failure." (PMID 29970016, 2018).